MAPKAPK3 (MAPK activated protein kinase 3)
Description:
Stress-activated serine/threonine-protein kinase involved in cytokines production, endocytosis, cell migration, chromatin remodeling and transcriptional regulation. Following stress, it is phosphorylated and activated by MAP kinase p38-alpha/MAPK14, leading to phosphorylation of substrates. Phosphorylates serine in the peptide sequence, Hyd-X-R-X(2)-S, where Hyd is a large hydrophobic residue. MAPKAPK2 and MAPKAPK3, share the same function and substrate specificity, but MAPKAPK3 kinase activity and level in protein expression are lower compared to MAPKAPK2. Phosphorylates HSP27/HSPB1, KRT18, KRT20, RCSD1, RPS6KA3, TAB3 and TTP/ZFP36. Mediates phosphorylation of HSP27/HSPB1 in response to stress, leading to dissociate HSP27/HSPB1 from large small heat-shock protein (sHsps) oligomers and impair their chaperone activities and ability to protect against oxidative stress effectively. Involved in inflammatory response by regulating tumor necrosis factor (TNF) and IL6 production post-transcriptionally: acts by phosphorylating AU-rich elements (AREs)- binding proteins, such as TTP/ZFP36, leading to regulate the stability and translation of TNF and IL6 mRNAs. Phosphorylation of TTP/ZFP36, a major post-transcriptional regulator of TNF, promotes its binding to 14-3-3 proteins and reduces its ARE mRNA affinity leading to inhibition of dependent degradation of ARE-containing transcript. Involved in toll-like receptor signaling pathway (TLR) in dendritic cells: required for acute TLR-induced macropinocytosis by phosphorylating and activating RPS6KA3. Also acts as a modulator of Polycomb-mediated repression.
Synonyms: MAPKAP-K3; MAPKAPK-3; MK-3; 3pK; MAPKAP3; MK3; MDPT3
Tractability: Small molecule: a structure with a bound ligand is known; a high-quality ligand is known; it belongs to a druggable protein family. PROTAC: it is named in the literature on targeted protein degradation; ubiquitination databases record sites on it; a small molecule that binds it is known.
Target class: CAMK protein kinase group; Kinase; Enzyme; CAMK protein kinase MAPKAPK subfamily; Protein Kinase; CAMK protein kinase MAPKAPK family
Gene: Protein-coding gene on chromosome 3 (50,611,487 to 50,651,017, forward strand). Ensembl gene ENSG00000114738.
Subcellular location: Nucleus; Cytoplasm
Subcellular location (Human Protein Atlas): Nucleoplasm
Pathways (Reactome):
Signal Transduction: VEGFA-VEGFR2 Pathway; p38MAPK events
Cellular responses to stimuli: Oxidative Stress Induced Senescence
Immune System: activated TAK1 mediates p38 MAPK activation
Gene Ontology:
Molecular function: protein binding; protein serine/threonine kinase activity; MAP kinase kinase activity; mitogen-activated protein kinase binding; ATP binding; protein kinase activity; protein serine kinase activity
Biological process: MAPK cascade; response to cytokine; intracellular signal transduction; macropinocytosis; response to lipopolysaccharide; signal transduction; toll-like receptor signaling pathway; vascular endothelial growth factor receptor signaling pathway
Cellular component: cytoplasm; nucleoplasm; nucleus; cytosol
Genetic constraint (gnomAD): Loss-of-function variants: 34 observed, 48 expected, observed/expected ratio (o/e) 0.71, 90% interval 0.54 to 0.94. The upper end of that interval is the gene's LOEUF score, 0.94, which puts it in group 4 of 6, group 1 being the genes least tolerant of losing a copy. Missense variants: 360 observed, 469.02 expected, observed/expected ratio (o/e) 0.77, 90% interval 0.7 to 0.84. Synonymous variants: 159 observed, 178.4 expected, observed/expected ratio (o/e) 0.89, 90% interval 0.78 to 1.02.
Homologues: Orthologues: chimpanzee MAPKAPK3 (99% identical), rabbit MAPKAPK3 (97% identical), pig MAPKAPK3 (96% identical), dog MAPKAPK3 (96% identical), mouse Mapkapk3 (95% identical), guinea pig MAPKAPK3 (94% identical), rat Mapkapk3 (94% identical), macaque MAPKAPK3 (88% identical), tropical clawed frog mapkapk3 (76% identical), zebrafish mapkapk3 (75% identical), Drosophila melanogaster MAPk-Ak2 (58% identical). Paralogues in human: MAPKAPK2 (68% identical), MAPKAPK5 (40% identical), CAMK4 (31% identical), MKNK2 (30% identical), MKNK1 (29% identical), DCX (14% identical).
Diseases named in the same sentence as MAPKAPK3 in open-access papers:
MAPKAPK3 is named in the same sentence as 25 diseases in open-access papers, as found by Europe PMC text mining. Sharing a sentence is not in itself a finding about the gene and the disease. The quoted sentences say what the papers report.
colon cancer (2 papers, 2023 to 2026). "The rest three genes KTI12, MAPKAPK3, and RPUSD2 haven’t been well-studied in colon cancer." (PMID 37701039, 2023).
melanoma (2 papers, 2005 to 2020). A malignant, usually aggressive tumor composed of atypical, neoplastic melanocytes. "Psen2 encodes the protein presenilin-2, a MYC target increased in melanoma cells, whereas Mapkapk3 is a member of the p38 pathway that promotes autophagy." (PMID 32831131, 2020).
non-small cell lung carcinoma (2 papers, 2019 to 2022). A group of at least three distinct histological types of lung cancer, including non-small cell squamous cell carcinoma, adenocarcinoma, and large cell carcinoma. "Multiple nonhistone proteins are methylated by SMYD2 to achieve these effects on tumors, for example, MAPKAPK3 in PDAC and ALK in non-small-cell lung cancer (NSCLC)." (PMID 31370883, 2019). "In non-small-cell lung cancer (NSCLC), multiple nonhistone proteins are modified by SMYD2 mediated methylation, and effects on tumors are generated by the modified activity of signaling pathways, for example, MAPKAPK3 in PDAC and ALK." (PMID 36520265, 2022).
pancreatic ductal adenocarcinoma (2 papers, 2021 to 2022). An infiltrating adenocarcinoma that arises from the epithelial cells of the pancreas. "SMYD2 promotes lysine methylation of MAPKAPK3 at site 355 in pancreatic ductal adenocarcinoma." (PMID 35432530, 2022). "In pancreatic ductal adenocarcinoma, SMYD2 promotes tumor formation by promoting the methylation of Lys355 of human mitogen-activated protein kinase activated protein kinase 3 (MAPKAPK3)." (PMID 34335697, 2021).
Sepsis (2 papers, 2021 to 2023). Sepsis is defined as life-threatening organ dysfunction caused by a dysregulated host response to infection. "This study predicted a total of 109 drug targets based on the Drugbank23 database using the structure of MEL, which yielded three shared sepsis‐related genes (PIK3CG, ADA, and MAPKAPK3)." (PMID 36684068, 2023).
colorectal cancer (1 paper, 2020). A primary or metastatic malignant neoplasm that affects the colon or rectum. "However, while MAPKAPK3 has already been suggested as a potential biomarker for colorectal cancer further investigations are still in order." (PMID 32735660, 2020).
diabetes (1 paper, 2021).
glioma (1 paper, 2022). A benign or malignant brain and spinal cord tumor that arises from glial cells (astrocytes, oligodendrocytes, ependymal cells). "We found that MAPKAPK3 was highly expressed in glioma tissues and high MAPKAPK3 expression was associated with poor prognosis." (PMID 35285415, 2022). "MAPKAPK3 was co-expressed with TSPO in glioma tissues, whereas suppression of TSPO inhibited the expression of MAPKAPK3 in U251 and U87 cells and increased its mRNA degradation." (PMID 35285415, 2022). "Knockdown of HUR significantly reduced the expression of MAPKAPK3, as well as the proliferation and mobility of glioma cells; overexpression of MAPKAPK3 reversed the effects of HUR knockdown." (PMID 35285415, 2022). "Furthermore, rescue experiments show that the HUR/MAPKAPK3 axis accounts for the TSPO-mediated effects on glioma cell proliferation and mobility." (PMID 35285415, 2022). "Together, our present study indicated that TSPO may promote the nuclear–cytoplasmic shuttling of HUR, thus increasing the mRNA stability of MAPKAPK3 and promoting the proliferation and mobility of glioma cells." (PMID 35285415, 2022). "Close attention must be paid to the MAPK signaling pathway, in which a member of this pathway, named MAPKAPK3, was significantly co-expressed with TSPO in both TCGA glioma tissues and our glioma tissues." (PMID 35285415, 2022). "It is demonstrated that TSPO recruits HUR shuttling from the nucleus to cytoplasm and enhances the stability of the MAPKAPK3 mRNA, activating the oncogene CREB, thus promoting glioma cell proliferation and mobility." (PMID 35285415, 2022). "Our findings underscore that the HUR/MAPKAPK3 axis is a key downstream of TSPO, and targeting this axis may be a potential strategy for blocking the effects of TSPO, contributing to glioma therapy." (PMID 35285415, 2022). "The HUR/MAPKAPK3 axis may be key targets for blocking the effects of TSPO and may contribute to glioma therapy." (PMID 35285415, 2022). "Increased TSPO in glioma cells may attract HUR to shuttle from the nucleus to the cytoplasm, promoting HUR binding and increasing the mRNA stability of MAPKAPK3, thus activating the oncoprotein CREB and promoting glioma cell proliferation and mobility." (PMID 35285415, 2022). "In addition, overexpression of MAPKAPK3 and HUR could reverse TSPO-silencing-induced inhibition of glioma cell proliferation and mobility." (PMID 35285415, 2022).
invasive breast carcinoma (1 paper, 2018). A carcinoma that infiltrates the breast parenchyma. "Loss of genes such as MAPKAPK3 was reported in invasive breast carcinomas." (PMID 30337938, 2018).
kidney cancer (1 paper, 2021). Primary or metastatic malignant neoplasm involving the kidney. "We found that five aging-related genes (DUSP22, MAPK14, MAPKAPK3, STAT1, and VCP) from kidney cancer patients were significantly related to patient survival." (PMID 34207247, 2021).
leukemia (1 paper, 2021). A malignant (clonal) hematologic disorder, involving hematopoietic stem cells and characterized by the presence of primitive or atypical myeloid or lymphoid cells in the bone marrow and the blood. "As a novel regulator for APA events, FIP1L1 can regulate the 3’UTR lengthening of leukemia-associated genes, including NRAS, BAALC, and MAPKAPK3." (PMID 34195183, 2021).
lung adenocarcinoma (1 paper, 2016). A carcinoma that arises from the lung and is characterized by the presence of malignant glandular epithelial cells. "Endogenous methylation of MAPKAPK3 at K355 was observed in human SW1990 PDAC cells as well as human H358 and H441 lung adenocarcinoma cells, and this signal decreased upon RNAi-mediated depletion of SMYD2." (PMID 26988419, 2016).
lung carcinoma (1 paper, 2017). "Low levels of NR_028502.1, NR_028505.1, NR_051978.1, NR_136240.1, MAPKAPK3, MYLIP were associated with poor survival in patients with lung cancer." (PMID 28968955, 2017).
renal cell carcinoma (1 paper, 2021). "As a result, five aging-related genes (DUSP22, MAPK14, MAPKAPK3, STAT1, and VCP) in normal tissues were found to be significantly associated with a worse survival outcome in patients with renal cell carcinoma (RCC)." (PMID 34207247, 2021).
triple-negative breast carcinoma (1 paper, 2023). An invasive breast carcinoma which is negative for expression of estrogen receptor (ER), progesterone receptor (PR), and human epidermal growth factor receptor 2 (HER2). "MAPKAPK3, AKT3, CDK5, IGF1R, and MAPK11 are potential prognostic markers and therapeutic targets of curcumin in patients with triple-negative breast cancer." (PMID 37569854, 2023).
cancer (9 papers, 2005 to 2025). A tumor composed of atypical neoplastic, often pleomorphic cells that invade other tissues. "Accumulating evidence revealed that positive expression of MAPKAPK3 is associated with a poor prognosis in several cancers." (PMID 35285415, 2022). "The genes associated with cancer Hallmarks were GNAI2, RHOA, MAPKAPK3, HYAL1, and CISH, while the most connected were RHOA, MST1R, and ATRIP." (PMID 40028213, 2025). "This pathway has many functions during stress response and cancer development, but MAPKAPK3 is also able to phosphorylate Beclin 1, thereby positively regulating starvation-induced autophagy." (PMID 35454789, 2022). "Specific genes were highlighted for Hallmarks of Cancer NAG-related genes (PTPRJ and NDUFS) were linked to cell proliferation and growth; IGC genes (GNAI2, RHOA, MAPKAPK3, MST1R) to genomic instability, metastasis, and arrest of cell death; and DGC genes to energy metabolism and immune evasion." (PMID 40028213, 2025). "Together, these results suggest that MAPKAPK3 could be a cancer-relevant cytoplasmic target of SMYD2." (PMID 26988419, 2016).
tumor (9 papers, 2005 to 2026). "MAPKAPK3 may serve as a key functional gene associated with tumor progression and microenvironment remodeling within the CMA-related prognostic framework." (PMID 42317342, 2026). "Among these genes, four genes (TIMP1, MAPK13, MAPKAPK2 and MAPKAPK3) are known to regulate cell proliferation, and MMP2 and MMP9 control tumour-associated tissue remodelling; PIK3CD is involved in the immune response, and AKT2 regulates tumourigenesis." (PMID 32999349, 2020). "Tumorigenic and also tumor-suppressive functions of MAPKAPK3 have been described." (PMID 35742860, 2022). "Indeed, significant down-regulation of MAPK3, MAP2K2, MAPKAPK3, ELK1 and up-regulation of the phosphatase DUSP1 was found in the reprogrammed tumours." (PMID 29662623, 2018). "It was also found that ERK pathway was enriched in tumor specimen after receiving chemotherapy, several ERK pathway component genes expression elevated in KEGG and REACTOME GSEA results, such as MAPK10, MAPK13, MAPK11 and MAPKAPK3." (PMID 29296238, 2017). "The Gal4-dependent upregulation of PURB (transcriptional activator protein Pur-beta) and MAPKAPK3 (MAPK-Activated Protein Kinase 3) expression, as well as the downregulation of BTF3 (Basic Transcription Factor 3) and BCAR1(Breast Cancer Anti-Estrogen Resistance Protein 1), could be confirmed." (PMID 35742860, 2022).
infection (3 papers, 2020 to 2023). The state of being infected such as from the introduction of a foreign agent such as serum, vaccine, antigenic substance or organism. "Moreover, MAPKAPK3 is a member of stress-responsive kinases that induce autophagy in terms of stress (inflammation, infection, and starvation) and thus determines cell fate." (PMID 33343640, 2020). "In NHBE and THP-1 cells, five mitogen-activated protein kinase (MAPK) family members (MAP2K3, MAP2K6, MAPKAPK2, MAPKAPK3, MAPKAPK5) showed decreased activity or no significant change during pH1N1 infection, and increased activity during H3N2 and H5N1 infection." (PMID 37758692, 2023).
MAPKAPK3 also shares sentences with these, for which no sentence is quoted: Breast (1 paper); breast carcinoma (1); endometriosis (1); insulin-resistant (1); multiple sclerosis (1); osteoarthritis (1); sarcopenia (1).